PIN1 (peptidylprolyl cis/trans isomerase, NIMA-interacting 1)
Diseases named in the same sentence as PIN1 in open-access papers (continued):
Sharing a sentence is not in itself a finding about the gene and the disease.
cancer (continued). "Conversely cancer tissues seem to gain an improved control on oxidative damage as shown by the selective reduction of carbonyl adducts on key detoxifying/pro-survival proteins such as ERp57, Anx2, Serpin B3, Pin1 and GAPDH." (PMID 22470562, 2012). "Pin1 has been found in both nucleus and cytoplasm in cancer cells, and it is at this point unclear what biological significance a variation in the subcellular distribution of Pin1 may have." (PMID 19077306, 2008). "For therapeutic purposes, the diversity of signaling cascades that Pin1 is involved in may be an advantage and provide the broad inhibitory coverage of targets that may be needed to treat cancer efficiently." (PMID 19077306, 2008). "Resistance to erbB2-directed cancer treatments is an unsolved clinical problem, and therefore we asked if Pin1 inhibition could enhance the efficacy of other signaling inhibitors that target erbB2-dependent pathways." (PMID 19077306, 2008). "Activation of the KRAS pathway by Pin1 is particularly important for the development of pancreatic ductal adenocarcinoma (PDAC), one of the most aggressive and lethal tumors, which is projected to become the second leading cause of cancer-related deaths by 2030 in the United States." (PMID 41322199, 2025). "In this approach, Sulfopin, or a combination of ATRA and ATO were used to inhibit Pin1, and it highlights the potential of potent Pin1-inhibitors for clinical treatment either on their own or in combination with immunochemotherapy to render aggressive and resistant cancers curable." (PMID 38745861, 2024). "Notably, the protein Pin1 serves a significant dual function in cancer and neurodegeneration." (PMID 38534454, 2024). "Similarly, Pin1 exhibits higher levels primarily in cancer but lower levels in AD." (PMID 38534454, 2024). "Moreover, cinobufacini injection (CI), an aqueous extract of Cutis bufonis, has been demonstrated to dose-dependently inhibit Pin1 enzyme activity, resulting in the impaired expression of Pin1 both in vitro and in vivo, and is used clinically in cancer therapy in China." (PMID 39624096, 2024). "Pin1 also directly interacts with and regulates the stability, nuclear localization, and transcriptional capabilities of c-myelocytomatosis (c-MYC)—a transcription factor implicated in many cancers that prominently contributes to cell proliferation, survival, and stemness." (PMID 38745861, 2024). "Consequently, therapeutic strategies targeting Pin1 could enhance genomic stability, inhibit cancer proliferation, and reduce metastasis." (PMID 39624096, 2024). "KPT-6566 is a covalent Pin1 inhibitor that modifies C113 with the addition of a sulfanyl-acetate group via a disulfide bond; this reaction releases a quinone-mimicking drug that generates reactive oxygen species (ROS) and damages DNA, further contributing to Pin1-mediated cell death in cancer cells." (PMID 38745861, 2024). "Indeed, we found that PIN1 and NRF2 expression was upregulated in PDAC cells cultured with stiff substrate, suggesting the physical effects of ECM on cancer cells are involved in activating the PIN1/NRF2 axis, which represses the production of ROS and maintains the redox balance." (PMID 36834887, 2023). "Therefore, targeting Pin1 offers a unique and promising approach to eradicate this deadly cancer." (PMID 36770689, 2023). "Besides cancer, a number of studies highlighted the possible involvement of PIN1 in NDDs." (PMID 36923654, 2023). "The reason could be that targeting FKBP and Pin1 is more complicated due to their essential and heterogenous functions in different tissues such as in neurons and cancer cells, complex network of interacting proteins and pathways being affected, and inhibitors not being specific to the isoform." (PMID 37508437, 2023).
cancer (continued). "Peptidylprolyl cis-trans isomerase NIMA-interacting 1 (Pin1) is a regulator that specifically interacts with phosphorylated Ser/Thr-Pro (pS/T-P) motifs and catalyzes cis/trans isomerization, leading to conformational changes of its substrates that are involved in cancer development." (PMID 38089883, 2023). "Therefore, targeted inhibition of Pin1 will be able to inhibit a range of cancer pathways without causing obvious side effects." (PMID 36915713, 2023). "Furthermore, Pin1 is often highly expressed in cancer cells." (PMID 36569330, 2022). "Pin1-induced transformational changes have strong biochemical effects on many proteins which may play an important role regulating cell growth and ROS-mediated diseases, such as Alzheimer’s and cancer." (PMID 35681549, 2022). "Furthermore, Pin1 may act as a trigger factor for cancer progression in tumorigenesis after HBV infection." (PMID 36393854, 2022). "While the clinical properties of these inhibitors remain to be assessed, it was reported that All‐trans retinoic acid, a drug used to treat promyelocytic leukemia expressing the PML‐RARα fusion protein, directly binds and inhibits PIN1, which may extend its use to other cancer types." (PMID 36214609, 2022). "Indeed, it is highly worthwhile to study Pin1’s role in diseases as it may prove to be an effective drug target, as shown in the example of cancer." (PMID 36111342, 2022). "Moreover, it has been reported that PIN1, an enzyme that changes the conformation of phosphoprotein, is overexpressed in malignant tumors such as BC and CC, and that patients with PIN1 overexpression are likely to develop MPCs; such patients should be screened for disease in time." (PMID 35756608, 2022). "They suggested that Pin1 inhibition disrupts the desmoplastic and immunosuppressive tumor microenvironment by acting on CAFs and causing lysosomal degradation of the PD-1 ligand PD-L1 and the gemcitabine transporter ENT1 in cancer cells, rendering pancreatic cancer eradicable by immunochemotherapy." (PMID 35629212, 2022). "Furthermore, Pin1 might reduce miRNA biogenesis by modulating the function of exporin-5 (XPO5) in cancers." (PMID 33807199, 2021). "However PML and Rb are downregulated by Pin1 in various human cancers." (PMID 33807199, 2021). "Therefore, Pin1 is regarded as an intriguing target for cancer therapy." (PMID 33807199, 2021). "Moreover, overexpression of Pin1 promotes centrosome amplification, which increased centrosomal microtubule nucleation and Rac1 activity, which disrupts normal cell–cell adhesion and promotes invasion in cancer cells." (PMID 33807199, 2021). "Interestingly, the total miRNA expression profile is generally downregulated in tumors and this could lead to Pin1 upregulation in cancers." (PMID 33807199, 2021). "Moreover, Pin1 participates in the cancer hallmarks through activating some oncogenes and growth enhancers, or inactivating some tumor suppressors and growth inhibitors, suggesting that Pin1 could be an attractive target for cancer therapy." (PMID 32296699, 2020). "Pin1 inhibitors also are being evaluated for their usefulness in cancer therapies; however, it is possible that side effects could be a concern for this targeting due to the number and diversity of important Pin1 substrates in the cell." (PMID 32426354, 2020). "Thus, Pin1 may be critical in balancing the cancer‐promoting and cancer‐suppressing effects of IL‐18." (PMID 32347623, 2020).
cancer (continued). "Therefore, DAPK1 might be involved in the development of cancer and AD by regulating Pin1 function through its phosphorylation of Ser71." (PMID 32195254, 2020). "Subsequently, the Pin1-induced Rb inactivation leads to the dissociation of E2F from Rb and increased E2F transcriptional activity, triggering the expression of cell cycle regulatory proteins and promoting cell cycle progression through the G1 checkpoint in cancer cells." (PMID 32296699, 2020). "Therefore, it is important to assess the effects of cancer therapies that target Pin1." (PMID 32010480, 2020). "However, due to the tumor heterogeneity, whether miR-628-5p targets PIN1 in other cancers and the circulatory miR-628-5p level acting as an indicator in different cancers require further investigation." (PMID 32703934, 2020). "Thus, in cancers, modifications of Pin1 by SENP1 may contribute to cell proliferation and tumorigenesis." (PMID 32195254, 2020). "Therefore, immunophilins and PIN1 are promising therapeutic targets for cancer treatment." (PMID 32268506, 2020). "Therefore, the overall tumor-promoting activity of Brd4 in cancer cells might result from the Pin1-mediated conformational change of Brd4, leading to more stabilized Brd4 and conformational change-associated transcriptional potential increase." (PMID 32266261, 2020). "However, it is not fully understood how PIN1 controls cancer and cancer stem cell development." (PMID 32258027, 2020). "Therefore, it was speculated that inhibiting Pin1 might be an effective way to conquer the aggressive cancers by simultaneously impacting on multiple oncogenic signaling pathways." (PMID 30934730, 2019). "In this study, we showed that the combination of biomarkers demonstrated a better prognostic value than either one of Pin1, RhoA or RhoC, suggesting that these factors act together in the cancer metastatic process and thus effect of downregulation of one factor could be compensated by the others." (PMID 31324164, 2019). "Thus, we propose that the Cdk/Pin1/Plk1 axis is a common feature of the activation of mitotic transcription factors, which may also be helpful to identify cancers with poor survival prognosis." (PMID 30321399, 2019). "Pin1 is frequently up-regulated in various cancer cell types whereas the E3-ubiquitin-ligase of RelA/p65 known as suppressor of cytokine signalling-1 (SOCS-1) is down-regulated or mutated, all of which favours the constitutive activation of NF-κB in those cancers." (PMID 30717249, 2019). "Notably, PIN1 has been found to interact with cyclin D1 in cancer cells." (PMID 32010690, 2019). "Hence, there is a possibility that targeting Pin1-YAP/TAZ signalling could be a potential anti-cancer target." (PMID 31015482, 2019). "However, what are the specific mechanisms of Pin1 in different cancer capabilities?" (PMID 30158600, 2018). "Another example is provided by the hypothesized role of PIN1 in promoting cancer cell migration." (PMID 30314361, 2018). "Interestingly, PIN1 expression is positively correlated with cyclin D1 expression in these cancers." (PMID 30534074, 2018). "In addition to cancer, PIN1 also plays a critical role in other human diseases." (PMID 30534074, 2018). "However, PML and pRb are downregulated by Pin1 in numerous cancers." (PMID 30158600, 2018). "Therefore, Pin1 represent a possible target for anti-cancer therapies." (PMID 30563268, 2018). "Finally, we examined and summarized the therapeutic potential of PIN1 inhibitors in cancer therapy." (PMID 30534074, 2018).
cancer (continued). "Given the fact that Pin1 promotes cancer development through activating more than 40 oncogenes/growth-promoting proteins and inactivating over 20 tumor suppressors, sorafenib induced Pin1 down-regulation might in part account for its multiple targeting effect in HCC." (PMID 28404959, 2017). "Furthermore, all-trans retinoic acid (ATRA), a known anticancer drug that inhibits and ultimately induces degradation of active Pin1 in cancer cells, also potently sensitized HCC cells to sorafenib-induced cell death at least in part through a caspase-dependent manner." (PMID 28404959, 2017). "With no surprise, the increased activity of Pin1 is closely associated with many kinds of cancers." (PMID 27029791, 2016). "Pin1 could be a useful a biomarker in human cancers and is a target for drug therapy." (PMID 25992900, 2015). "Therefore, by targeting these significant substrates, which contain phospho-Ser/Thr-Pro motifs, PIN1-induced conformational changes may function as a critical catalyst for the potentiation of multiple oncogenic signaling pathways during cancer development." (PMID 25120724, 2014). "Thus, this study shows that an important biological role of Pin1 is to regulate mRNA abundance and stability by interacting with specific RNA-binding proteins that may play a role in cancer progression." (PMID 24416409, 2014). "Hence, deregulated signaling in cancer may fuel a Notch-Pin1 feed-forward loop, strongly contributing to tumor progression." (PMID 24357640, 2014). "Similarly, we found the PIN1 −667T>C polymorphism did not contribute to cancer risk in overall comparison." (PMID 23976970, 2013). "However, the variability in the biological and clinical effects of PIN1 depending on the types of cancer remains unclear." (PMID 24179535, 2013). "Additionally, aberrant expression of PIN1 has been reported in various cancers." (PMID 23874525, 2013). "In addition, it has also been suggested that PIN1 expression may play a role as a prognostic indicator in human cancers occurring in the breast, lung and prostate." (PMID 24179535, 2013). "This Pin1-mediated reduction in FBXW7 expression contributes to tumorigenesis, highlighting Pin1 as a potential therapeutic target in cancer." (PMID 40534867, 2025). "In this study, we aim to characterize the expression and localization of Pin1 in various cell lines, including human lung fibroblasts (MRC-5) and cancer cell lines (A549, H1299), to determine the most appropriate model for studying PF." (PMID 41477119, 2025). "Pin1 is expressed to varying degrees in cancer, and the binding of the death domain of DAPK1 to Pin1 inhibits the function of Pin1." (PMID 39057063, 2024). "Pin1 played a key role in cancer metastasis and was the main target of ATRA-NPs against cancer metastasis." (PMID 36915713, 2023). "We aim to elucidate the molecular mechanism by which PIN1 and CDK1 cooperatively modulate pVHL stability, contribute to tumor progression and explore their therapeutic potential in the treatment of cancers with wild-type VHL including TNBC." (PMID 36813923, 2023). "Previously, PIN1 inhibition via Juglone, PiB, ATRA, 6,7,4′-THIF, KPT6566, and EGCG had been widely examined in various cancers." (PMID 36760500, 2023). "Overall, our study provides important preclinical evidence that targeting PIN1/CDK1 axis is an appealing strategy to suppress tumor growth and metastasis, and sensitize cancer cells to chemotherapies by stabilizing pVHL in TNBC." (PMID 36813923, 2023). "We further provide preclinical evidence demonstrating that targeting CDK1/PIN1 axis is a common and effective approach to suppress tumor progression of TNBC and other cancers harboring wild-type VHL including TNBC." (PMID 36813923, 2023).
cancer (continued). "Therefore, most of the currently available inhibitors have been characterized as anticancer agents in various cancer cell lines and mouse models, with the primary aim of suppressing tumor growth and/or preventing tumor recurrence, as well as enhancing the understanding of Pin1 biology." (PMID 37508437, 2023). "Additionally, Pin1 is overexpressed in most human cancers, and elevated Pin1 expression promotes cancer formation and is positively associated with an unfavorable prognosis; by contrast, lack of Pin1 hampers tumor development in mouse models." (PMID 35433695, 2022). "Previous work revealed PKM2 is translocated to the nucleus in human cancer cells in response to EGF, a process resulting from PKM2 successively binding to PIN1 (peptidylprolyl cis/trans isomerase, NIMA-interacting 1) and importin α5." (PMID 36476366, 2022). "Pin1 upregulates NF-κB expression and consequently promotes angiogenesis through increased VEGF expression in a number of cancers." (PMID 33807199, 2021). "Pin1 upregulates HDAC6 expression through stabilization of HDAC6 mRNA and protein, which consequently promotes cell motility in cancer cells." (PMID 33807199, 2021). "Overexpression of Pin1 in cervical cancer can increase nuclear retention of NF-κB and promote transactivation of STAT3, further promoting the occurrence of cancer 144-146." (PMID 33537091, 2021). "Pin1 also promotes the stability and transcriptional activity of HIF-1α to act a central regulator of glycolysis, cancer metabolism and cancer cell proliferation." (PMID 33807199, 2021). "Briefly, Pin1 promotes the stability and transcriptional activity of HIF-1α in human cancers or diseases." (PMID 33807199, 2021). "Pin1 interacts with KLF10 and promotes its protein degradation, blocking the anti-proliferative function of KLF10 in cancer cells." (PMID 32296699, 2020). "To investigate the function of IL‐18 in Pin1‐induced cancer progression, we transfected the IL‐18 siRNA into the MIA PaCa‐2 cells stably overexpressed Pin1." (PMID 32347623, 2020). "PIN1 regulates HER2, NOTCH1, NOTCH3, androgen receptor (AR) and estrogen receptor α (ERα), which are cancer-driving receptors." (PMID 32258027, 2020). "Regarding tumorigenesis, the cancer-specific ubiquitin ligase MAGE-A3/6-TRIM28 and the prolyl isomerase Pin1 participate in the ubiquitination and degradation of AMPK." (PMID 31971978, 2020). "Treatment of 100 nM of this peptide in cancer cell lines (HeLa and BT-474) increases the levels of PML and SMRT, and inhibits intracellular PIN1 activity." (PMID 32258027, 2020). "While PIN1 overexpression in cancer has been correlated with increased HIF-1α stability, the inverse is suggested to occur with AD whereby PIN1 promotes HIF-1α degradation via a GSK-3β-dependent mechanism." (PMID 33383924, 2020). "In this study, a novel liposomal formulation of Pin1 inhibitor API-1, named as API-LP, was developed for the purpose of enhancing the anti-cancer activity through an efficient delivery of API-1 to HCC cells." (PMID 31367251, 2019). "Lastly, we determined that a group of genes with reported connections to cancer and/or AD are regulated by PARN, Pin1 and tau, further supporting the idea of the functional interactions of these factors." (PMID 31749682, 2019). "In conclusion, Pin1 plays a major role in all steps of the NASH process, including fat accumulation, fibrosis, and, perhaps ultimately, cancer development." (PMID 31795496, 2019). "We demonstrate that Pin1 is highly overexpressed in human AML and is a promising therapeutic target to block multiple cancer-driving pathways in AML." (PMID 29848341, 2018).